MIRLET7A3 (microRNA let-7a-3)
Synonyms: hsa-let-7a-3; LET7A3; MIRNLET7A3; let-7a-3
Gene: MicroRNA gene on chromosome 22 (46,112,749 to 46,112,822, forward strand). Ensembl gene ENSG00000283990.
Gene Ontology:
Biological process: miRNA-mediated post-transcriptional gene silencing
Cellular component: RISC complex
Homologues: Orthologues: chimpanzee ptr-let-7a-3 (100% identical), macaque MIRLET7A3 (100% identical), guinea pig MIRLET7A3 (95% identical), mouse Mirlet7c-2 (92% identical), rat Mirlet7c2 (92% identical), dog MIRLET7A-1 (91% identical), tropical clawed frog xtr-let-7e-2 (84% identical), zebrafish dre-let-7e (82% identical). Paralogues in human: MIRLET7A1 (84% identical), MIRLET7F2 (81% identical), MIRLET7F1 (76% identical), MIRLET7G (73% identical), MIR98 (72% identical), MIRLET7C (72% identical), MIRLET7D (72% identical), MIRLET7A2 (70% identical), MIRLET7E (66% identical), MIRLET7I (65% identical).
Diseases named in the same sentence as MIRLET7A3 in open-access papers:
MIRLET7A3 is named in the same sentence as 2 diseases in open-access papers, as found by Europe PMC text mining. Sharing a sentence is not in itself a finding about the gene and the disease. The quoted sentences say what the papers report.
hepatocellular carcinoma (1 paper, 2018). A malignant tumor that arises from hepatocytes. "Methylation of MIRLET7A3 gene was reported to be the cause of this suppression in several cancers; however, it was not explicitly investigated in hepatocellular carcinoma (HCC)." (PMID 30733684, 2018).
MIRLET7A3 also shares sentences with these, for which no sentence is quoted: cancer (1 paper).